DPP4 (dipeptidyl peptidase 4)
Diseases named in the same sentence as DPP4 in open-access papers (continued):
Sharing a sentence is not in itself a finding about the gene and the disease.
diabetes (continued). "If the association between the risk of ischemic cerebrovascular disease and DPP-4 inhibitors use substantially exists, the drug of choice for management of type 2 diabetes mellitus can be suggested in Taiwan." (PMID 29213240, 2017). "Two clinical trials published in 2013 brought to public concern a possible risk of heart failure associated with the use of dipeptidyl-peptidase 4 (DPP-4) inhibitors in the treatment of type 2 diabetes mellitus." (PMID 27409676, 2016). "Teneligliptin, a novel, highly selective DPP-4 inhibitor, is an antidiabetic drug that improves glycemic control without causing weight gain or increasing hypoglycemic risk in patients with type 2 diabetes mellitus." (PMID 27652270, 2016). "The chronic use of DPP-4 inhibitors has been associated with reduced levels of resistin in mice, however sitagliptin cannot suppress resistin levels in patients with type 2 diabetes mellitus." (PMID 26811539, 2016). "There is a crosstalk between the AGEs-RAGE axis and DPP-4-incretin system in the pathogenesis of diabetes-associated disorders." (PMID 25582643, 2015). "This article summarizes the crosstalk between AGEs-RAGE axis and DPP-4-incretin system in the development and progression of diabetes-associated disorders and its therapeutic intervention, especially focusing on diabetic vascular complications." (PMID 25582643, 2015). "Inhibitors of DPP4 are used to treat diabetes and can cause fatigue, consistent with our observation of an association between DPP4 and low fatigue." (PMID 26694930, 2015). "Curiously, AGEs enhance the expression of DPP4 and its release, while DPP4 increases RAGE gene expression, suggesting the existence of a cross talk between the AGEs-RAGE axis and DPP4 in the pathogenesis of diabetes-associated complications." (PMID 26146634, 2015). "In the position statement of the American Diabetes Association and the European Association for the Study of Diabetes, metformin is the first drug of choice for type 2 diabetes, and DPP-4 inhibitors are cited as one of second-line drugs." (PMID 24578754, 2014). "As a regulator of glucose homeostasis, an exogenous GLP-1 analogue or potentiating endogenous GLP-1 by DPP-4 inhibitors show promise for the treatment of type 2 diabetes mellitus (T2DM) associated with cardiovascular disease." (PMID 25194961, 2014). "Up-regulation of DPP-4 expression in renal glomeruli occurs during inflammation, and this phenomenon is associated with the development of diabetes-induced glomerulosclerosis." (PMID 23785355, 2013). "DPP4 deficiency delays the onset of diabetes but worsens dyslipidaemia and renal dysfunction induced by STZ." (PMID 23853775, 2013). "DPP-4′s dual role in glucose metabolism (diabetes) and cardiac pathology (HF) may explain its diagnostic supremacy for identifying periodontitis patients with HF + diabetes association at a 13.115 ng/mL cutoff." (PMID 40429343, 2025). "Additionally, rs7754840-C, associated with improved response to dipeptidyl peptidase-4 (DPP-4) inhibitors in people with diabetes mellitus, had a frequency of 76.1% in the PLQ population and 28.4% in European populations." (PMID 40949159, 2025). "DPP-4 inhibitor therapy can cause pancreatitis in diabetes patients." (PMID 40734861, 2025). "Research by our group suggests that the DPP4 rs17574 G allele may serve as a genetic marker for premature CAD (pCAD) in individuals with diabetes." (PMID 40249657, 2025). "The present study replicates the previously observed dementia risk reduction with SGLT2 inhibitor versus DPP4 inhibitor initiation in people with diabetes, but limited studies with adequate events have explored the association between continuous use of SGLT2 inhibitors and dementia aetiologies." (PMID 41420258, 2025).
diabetes (continued). "Additionally, single nucleotide polymorphisms in DPP-4 have been associated with responsiveness to drugs that target DPP-4, and with the risk of developing certain health conditions, including heart failure, type 2 diabetes mellitus, and dyslipidemia." (PMID 39024213, 2025). "The DPP4-mediated immune-metabolic alterations may help to explain the increased susceptibility of patients with diabetes to SARS-CoV-2 infection and their higher mortality rates." (PMID 40431631, 2025). "Among the SNPs predominant in African ancestry, rs7754840-C, associated with increased response to dipeptidyl peptidase 4 (DPP-4) inhibitors in people with diabetes mellitus, was present in 66.1% of the mean African allele frequency and 28.4% of the mean European allele frequency." (PMID 41149843, 2025). "Furthermore, DPP4 has been shown to contribute to aortic valve calcification and DPP4 inhibition was associated with lower risk of AS progression in patients with diabetes and mild to moderate AS." (PMID 41141478, 2025). "Gliptin, a dipeptidyl peptidase-4 inhibitor used to treat diabetes mellitus, can cause cough as a side effect, which may be attributed to the persistent cough of COVID-19." (PMID 38315527, 2024). "Therefore, we used a meta-analysis to determine the association between DPP4 inhibitors and cognitive impairment in type 2 diabetes mellitus." (PMID 38379936, 2024). "It was reported previously that DPP4 inhibition might reduce the increased risk of immediate death following a myocardial infarction associated with type 2 diabetes mellitus." (PMID 39359253, 2024). "Diabetes treatment with DPP4 is linked to higher GLP-1 levels." (PMID 36909158, 2023). "Moreover, a longer duration of diabetes was correlated with a lower risk of PD after DPP4 inhibitor treatment (p for interaction = 0.05)." (PMID 38110464, 2023). "Importantly, a lower abundance of DPP4 in SP has been linked to decreased sperm motility in males suffering from type 2 diabetes mellitus; thus, potentially explaining the decline of male fertility commonly observed in diabetic patients." (PMID 35883590, 2022). "Additional variants, in the DPP4, including those that contribute to diseases like diabetes or other disorders, could be important in terms of their affects on binding affinity and viral entry into host cells as well." (PMID 36188214, 2022). "Thus, overexpression of DPP4 in patients suffering from diabetes mellitus is linked with hyperglycemia development." (PMID 36355535, 2022). "DPP4 was widely associated with key proteins in diabetes mellitus." (PMID 34996987, 2022). "DPP4 is widely associated with key proteins in diabetes mellitus." (PMID 34996987, 2022). "Several studies also indicated that DPP4 inhibitors may prevent the progression of diabetes and improve the cognitive impairment associated with the disease by a modulation of inflammatory pathways." (PMID 35468904, 2022). "Due to the pathogenetic links between COVID-19 and diabetes mellitus and the hyperinflammatory response, with the hallmark cytokine storm developed very often during the disease, we dive deep into the functions of DPP4 on carbohydrate metabolism and immune system regulation." (PMID 36009573, 2022). "However, DPP4 also circulates in the plasma carrying catalytic activity even after shedding; besides, its higher level is associated with many diseases including diabetes." (PMID 36014373, 2022). "For example, retrospective cohort studies have shown that incretin-based therapies involving glucagon-like peptide 1 receptor agonists (GLP-1 RAs) and dipeptidyl peptidase 4 (DPP-4) inhibitors in patients with diabetes have been associated with an increased risk of pancreatic cancer." (PMID 34830886, 2021).
diabetes (continued). "Unequivocal evidence for the clinical importance of DPP4 stems from the fact that its inhibitors are well acknowledged in pharmacotherapy of diabetes, helping to control the risk of atherosclerosis by reducing LDL-C levels, increasing HDL-C levels, and lowering blood pressure." (PMID 34298827, 2021). "Here, patient’s TH17 cells showed reduced surface expression of CD26/DPP4 that positively correlated with increased plasma DPP4 activity arguing for TH17 cells as a source for the elevated plasma sCD26/DPP4 abundance associated with Diabetes mellitus type 2." (PMID 35003134, 2021). "In addition, the development in the field of ABCC8 gene-related diabetes has included de novo variants identified by new rapid molecular genetic features, symptoms, and medical therapy (sulfonylureas, DPP4-inhibitor)." (PMID 34631896, 2021). "DPP4 activity is associated with the onset and severity of obesity and diabetes." (PMID 34043673, 2021). "Indeed, DPP4 inhibition using the anti-diabetes drug Sitagliptin has been associated with reduced incidence of breast cancer in diabetes patients, and has an immune-mediated protective effect in several preclinical models." (PMID 33143089, 2020). "In any case, further clinical studies should be needed to clarify whether DPP-4 inhibitors could inhibit foam cell formation of macrophages and resultantly reduce the risk of cardiovascular events in patients with diabetes." (PMID 32646003, 2020). "In addition, we have pointed to many beneficial pleiotropic effects of DPP-4 inhibitors with protective role in renal and cardiovascular disorders as specific entities or type 2 diabetes mellitus associated comorbidities including myocardial regeneration." (PMID 32848788, 2020). "The present study aimed to compare the differences between the risk of hHF after using dapagliflozin and dipeptidyl peptidase-4 inhibitors (DPP-4i) as second-line drugs for the treatment of type 2 diabetes mellitus using the latest nationwide population data in Korea." (PMID 32571319, 2020). "Moreover, it has recently been suggested that the crosstalk between TLR-4 and dipeptidyl peptidase-4 (DPP-4)-incretin system is significantly associated with diabetes and CAD." (PMID 30654523, 2019). "Interestingly, however, a prospective cohort study found that treatment with DPP-4 inhibitors was associated with a reduced risk of acute kidney injury in patients with diabetes." (PMID 29491123, 2018). "As circulating DPP‐4 levels in human are closely associated with fat mass and type 2 diabetes mellitus 17, 33, the hormonal function of sDPP‐4 might be important." (PMID 30410858, 2018). "The findings complement the most recent findings from observational research and need to be considered within the context of other available alternative of diabetes therapy which have shown a lower risk of HF compared to DPP-4 inhibitors (i.e. SGLT2 inhibitors)." (PMID 30016946, 2018). "Whether dipeptidyl peptidase-4 inhibitor (DPP4i) is associated with a lower risk of new-onset atrial fibrillation (AF) in patients with diabetes remains unclear." (PMID 29258504, 2017). "Taken together, these findings suggest that DPP-4 inhibitor treatment may be beneficial in individuals with a high HGI in terms of further reducing the risk of complications from diabetes." (PMID 28182722, 2017). "Incretin-based therapies in patients with type 2 diabetes mellitus by using either the injection form of glucagon-like peptide-1 receptor (GLP-1R) agonists or the oral form of dipeptidyl peptidase-4 (DPP-4) inhibitors have been shown to increase the risk of thyroid cancer." (PMID 27029076, 2016). "Association of DPP4 polymorphisms with type 2 diabetes mellitus among Malaysian ethnic groups." (PMID 27111895, 2016). "DPP-4 inhibition may have a protective effect on cardiovascular diseases, which are a major cause of mortality in patients with diabetes." (PMID 26937254, 2016).
diabetes (continued). "Association of DPP4 polymorphisms with type 2 diabetes mellitus among Malaysian subjects." (PMID 27111895, 2016). "Genetic polymorphisms of the Dipeptidyl Peptidase 4 (DPP4) gene may play a role in the etiology of type 2 diabetes mellitus (T2DM)." (PMID 27111895, 2016). "So, this article summarizes the crosstalk between AGEs-receptor for AGEs (RAGE) axis and DPP-4-incretin system in the development and progression of diabetes-associated disorders and its therapeutic intervention, especially focusing on diabetic vascular complications." (PMID 25582643, 2015). "Our results indicate that DPP-4 inhibitor may have a potential to delay fibrotic progression caused by diabetic nephropathy while it is prescribed to patient with diabetes." (PMID 24755682, 2014). "Identification of factors underlying the use of DPP-4 inhibitors may enhance rational use of drugs and, thus, diabetes care in T2DM patients." (PMID 25258626, 2014). "Though we could not, in our studies, directly attribute the low expression of insulin genes to DPP4, the association of very high DPP4 with diabetes is a confirmed phenomenon." (PMID 22291902, 2012). "In the context of personalized medicine and pharmacogenetics, the identification of high-risk DPP4 genotypes could enable more tailored therapeutic approaches for patients with type 2 diabetes mellitus, helping clinicians balance glycemic control with autoimmune disease risk." (PMID 41373842, 2025). "The findings of our study support the evidence that DPP-4 and Gal-3 could be considered markers for periodontitis associated with heart failure and diabetes, with DPP-4 being more upregulated in association with diabetes, and Gal-3 with heart failure, motivating further research." (PMID 40429343, 2025). "Molecular docking prediction studied results showed that all 27 active compound molecules from mango leaves could bind to the key interacting residues of 3 diabetes-causing enzymes, including GSK3β, DPP-4, and GLP-1R with the promising binding affinities (Table A1)." (PMID 41465578, 2025). "In this study, we investigated the association of long-term use of a dipeptidyl peptidase-4 inhibitor (DPP-4i) with the risk of diabetic retinopathy (DR) in patients with diabetes mellitus (DM)." (PMID 40308768, 2025). "Dipeptidyl peptidase-4 (DPP-4) inhibitors are promising medicines for treating type 2 diabetes mellitus (DM) and are expected to provide advantages over traditional DM treatments, including a low risk of hypoglycemia and weight gain." (PMID 38258116, 2024). "Similarly, patients with diabetes have a higher prevalence of psoriasis, which may be associated with insulin use, and DPP-4 inhibitor, a drug used for diabetes, has been shown to ameliorate psoriasis." (PMID 36837593, 2023). "The level of DPP-4 in the spermatozoa of patients with diabetes is much lower than that in normal healthy males, which could explain the loss of male fertility linked to diabetes." (PMID 37893048, 2023). "However, it remains unknown whether DPP-4 inhibitors are functional in treating diabetes-associated cognitive dysfunction." (PMID 39280108, 2022). "Newly synthesized adamantane derivatives or DPP4 inhibitors might have important roles in the future in prevention and treatment of cognitive impairment caused by inflammatory events in patients with diabetes or related diseases." (PMID 35468904, 2022). "The reasons for this discrepancy remain uncertain, although clinical differences in the patients’ background, such as concomitant drugs and severity of diabetes and CV risk may, in part, influence the effectiveness of DPP-4 inhibitors on carotid atherosclerosis." (PMID 27619983, 2016). "The American Diabetes Association/European Association for the Study of Diabetes position statement and the American Association of Clinical Endocrinologists/American College of Endocrinology algorithm suggest the use of DPP-4 inhibitors as a second option when metformin fails." (PMID 26500706, 2015).
diabetes (continued). "Therefore, given the atherosclerosis-promoting properties of AGE-RAGE axis, although the reason why DPP-4 caused vascular damage in diabetes remains unclear, DPP-4 itself might be involved in diabetic vascular injury." (PMID 23984879, 2013). "This has spurred research into potential therapeutic agents from natural sources that can inhibit both protein tyrosine phosphatase 1B (PTP1B) and dipeptidyl peptidase 4 (DPP4), which are implicated in these diabetes effects." (PMID 42007177, 2026). "Dipeptidyl peptidase-4 (DPP-4) inhibitors, though developed for diabetes, have shown renoprotective potential." (PMID 41601976, 2026). "Inhibition of dipeptidyl peptidase 4 (DPP-4) is a crucial therapeutic strategy for the management of type 2 diabetes mellitus (T2DM)." (PMID 41658155, 2026). "It positively affects diabetes by inhibiting dipeptidyl peptidase-4 (DPP-4), α-glucosidase, and α-amylase, while simultaneously increasing pancreatic insulin secretion and improving insulin sensitivity in organs." (PMID 41641144, 2026). "Molecular docking was performed against key diabetes-related enzymes, including α-amylase, α-glucosidase, and dipeptidyl peptidase-4, followed by validation through enzyme inhibition assays." (PMID 42194048, 2026). "Regarding concomitant medications for diabetes, dipeptidyl peptidase-4 (DPP-4) inhibitors were the most commonly administered, followed by metformin and/or SGLT2is." (PMID 39861190, 2025). "This approach presents a cost-effective and reliable alternative to traditional vivo screening, offering valuable support for the identification and classification of biologically active DPP-4 inhibitors in the treatment of type 2 diabetes mellitus (T2DM)." (PMID 40761758, 2025). "DPP4 inhibitors, such as saxagliptin, alogliptin, sitagliptin, vildagliptin, and linagliptin, are used in the treatment of type-2 diabetes mellitus (T2DM)." (PMID 41134486, 2025). "Recent research constantly indicates that DPP-4 inhibitors’ anti-inflammatory properties help to mitigate macro- and micro-vascular endothelial damage in diabetes." (PMID 40429343, 2025). "Sitagliptin, a dipeptidyl peptidase-4 inhibitor, has shown beneficial effects in diabetes-induced retinal neurodegeneration." (PMID 41515932, 2025). "The uniformly high correlations in P+HF+D patients suggest that diabetes intensifies the inflammation–destruction axis, with DPP-4 serving as the lead biomarker." (PMID 40429343, 2025). "Through its enzymatic function, DPP4 regulates insulin secretion and serves as a key therapeutic target in type 2 diabetes mellitus, where its inhibition enhances GLP−1 activity to promote glycemic control." (PMID 41334589, 2025). "A subsequent systematic review and meta-analysis confirmed a lower incidence of obesity-associated cancers and reduced all-cause mortality among patients with diabetes and obesity treated with GLP-1RAs compared to those using DPP-4 inhibitors." (PMID 41300964, 2025). "Linagliptin, a selective dipeptidyl peptidase-4 (DPP-4) inhibitor that was originally discovered as an antidiabetic drug for treating type 2 diabetes mellitus, was able to restore critical proteins and the balance between autophagy and apoptosis." (PMID 39567405, 2025). "Dipeptidyl peptidase-4 (DPP-4) inhibitors have been widely applied to treat diabetes via inhibiting degradation of GLP-1 to regulate insulin secretion." (PMID 40810069, 2025). "Due to the limited data on DPP-4’s role in diabetes and obesity, especially in the digestive system, this study investigated its local effects by comparing DPP-4 levels in small intestinal tissue between OB+/DM− and OB+/DM+ patients." (PMID 40142315, 2025). "One decisive therapeutic target for managing Type 2 Diabetes Mellitus (T2DM) is the Dipeptidyl Peptidase-4 (DPP-4) enzyme, which plays a key role in regulating glucose metabolism." (PMID 40761758, 2025).